MIR4642 (microRNA 4642)
Synonyms: hsa-mir-4642
Gene: MicroRNA gene on chromosome 6 (44,435,641 to 44,435,722, forward strand). Ensembl gene ENSG00000266619.
Diseases named in the same sentence as MIR4642 in open-access papers:
MIR4642 is named in the same sentence as 1 disease in open-access papers, as found by Europe PMC text mining. Sharing a sentence is not in itself a finding about the gene and the disease.
MIR4642 shares sentences with these, for which no sentence is quoted: Bell's palsy (1 paper).